NEK11 (NIMA related kinase 11)
Description:
Protein kinase which plays an important role in the G2/M checkpoint response to DNA damage. Controls degradation of CDC25A by directly phosphorylating it on residues whose phosphorylation is required for BTRC-mediated polyubiquitination and degradation.
Synonyms: FLJ23495
Tractability: Small molecule: a high-quality ligand is known; it belongs to a druggable protein family. PROTAC: ubiquitination databases record sites on it; a small molecule that binds it is known.
Target class: Kinase; Protein Kinase; Other protein kinase group; Enzyme; Other protein kinase Nek11; Other protein kinase NEK family
Gene: Protein-coding gene on chromosome 3 (131,026,850 to 131,353,043, forward strand). Ensembl gene ENSG00000114670.
Subcellular location: Nucleus; Nucleus, nucleolus
Subcellular location (Human Protein Atlas): Nucleoplasm
Pathways (Reactome):
Cell Cycle: Ubiquitin-Mediated Degradation of Phosphorylated Cdc25A
Gene Ontology:
Molecular function: ATP binding; protein binding; protein serine kinase activity; protein serine/threonine kinase activity; protein kinase activity
Biological process: intracellular signal transduction; mitotic intra-S DNA damage checkpoint signaling; protein phosphorylation; regulation of mitotic cell cycle phase transition
Cellular component: nucleolus; nucleoplasm; nucleus
Genetic constraint (gnomAD): Loss-of-function variants: 46 observed, 50.38 expected, observed/expected ratio (o/e) 0.91, 90% interval 0.72 to 1.17. The upper end of that interval is the gene's LOEUF score, 1.17, which puts it in group 5 of 6, group 1 being the genes least tolerant of losing a copy. Missense variants: 577 observed, 604.6 expected, observed/expected ratio (o/e) 0.95, 90% interval 0.89 to 1.02. Synonymous variants: 206 observed, 211.19 expected, observed/expected ratio (o/e) 0.98, 90% interval 0.87 to 1.1.
Homologues: Orthologues: chimpanzee NEK11 (99% identical), pig NEK11 (80% identical), dog NEK11 (74% identical), mouse Nek11 (72% identical), rat Nek11 (70% identical), rabbit NEK11 (67% identical), tropical clawed frog nek11 (56% identical), zebrafish nek11 (50% identical). Paralogues in human: NEK5 (25% identical), NEK3 (22% identical), NEK9 (22% identical), NEK8 (22% identical), NEK2 (19% identical), NEK10 (18% identical), NEK7 (15% identical), NEK6 (15% identical).
Diseases named in the same sentence as NEK11 in open-access papers:
NEK11 is named in the same sentence as 21 diseases in open-access papers, as found by Europe PMC text mining. Sharing a sentence is not in itself a finding about the gene and the disease. The quoted sentences say what the papers report.
breast carcinoma (4 papers, 2020 to 2023). "Furthermore, NEK8 is known to play a role in gastric cancer cells and breast cancer, while NEK11 is known to play a role in ovarian cancer." (PMID 34834441, 2021). "The expression level of NEK6 in breast cancer cells (MCF-7 and SK-BR-3) was higher than that in normal breast epithelial cells in MCF-10A, and the expression level of NEK8 and NEK11 was higher than that in normal epithelial cells in MCF-7 (p < 0.01)." (PMID 35368696, 2022). "The expression of NEK2, NEK6, and NEK11 were related to colorectal cancer, NEK2, NEK3, NEK5, NEK6, and NEK8 to breast cancer, and NEK2 and NEK6 to prostate cancer." (PMID 31906878, 2020). "The mRNA level analysis of NEK genes in breast cancer cell lines and breast cancer patients from various data sources revealed that NEK2, NEK4, NEK5, NEK6, NEK8, and NEK11 are overexpressed in breast cancer and may be involved in breast cancer development." (PMID 37627077, 2023).
ovarian carcinoma (4 papers, 2015 to 2022). A malignant neoplasm originating from the surface ovarian epithelium. "Furthermore, recent studies have linked Nek11 loss with drug resistance in ovarian cancer." (PMID 26501353, 2015). "They concluded that, in 586 cases of ovarian serous cystadenocarcinomas and cisplatin-resistant A2780 ovarian cancer cells, NEK11 mRNA is downregulated." (PMID 32294979, 2020). "Furthermore, NEK11 was found to interact with 22 proteins and 4 small molecules related to drug resistance in ovarian cancer." (PMID 32294979, 2020).
colorectal cancer (3 papers, 2013 to 2020). A primary or metastatic malignant neoplasm that affects the colon or rectum. "The Nek11 kinase is a potential mediator of the DNA damage response whose expression is upregulated in early stage colorectal cancers (CRCs)." (PMID 26501353, 2015). "Nek11, a member of the NIMA-related kinase family, phosphorylates Cdc25a and controls its degradation; Cdc25a phosphorylation is required for cell cycle progression in colorectal cancer cells." (PMID 23555558, 2013).
Colon cancer (2 papers, 2013 to 2022). "As part of the physiological barrier induced by DNA damage, NEK11 was overexpressed in precancerous lesions of 35% of colorectal adenomas and colon cancer, and its high expression level is associated with low tumor grade and weak invasive ability." (PMID 35105934, 2022). "Colon cancer-related genes such as Nek11, Gucy2c, Srp9, Tle6, and Pdgfrl were also overrepresented in the time-course clusters identified by the MNI analysis in the epididymal and subcutaneous fat tissues and gastrocnemius muscle of mice with diet-induced obesity." (PMID 23555558, 2013).
colorectal adenoma (2 papers, 2015 to 2022). An adenoma that arises from the colon or rectum. "Nevertheless, Nek11 has also been reported to be a potentially relevant cancer biomarker as elevated Nek11 expression was detected in a set of colorectal adenomas." (PMID 26501353, 2015).
colorectal tumours (1 paper, 2015). "We chose to focus on CRC due to the demonstration that Nek11 expression is increased in early stage colorectal tumours before being down-regulated in more advanced tumours." (PMID 26501353, 2015).
familial renal glucosuria (1 paper, 2020). Familial Renal Glucosuria (FRG) is characterized by the presence of persistent isolated glucosuria in the absence of both generalized proximal tubular dysfunction and hyperglycemia. "In conclusion, WES identified DNA variants in four different genes as potential novel causes of IKH, suggesting that IKH is a heterogeneous disorder that can be split into several novel diseases: NCOR1-KH, IGF2BP1-KH, SGLT2-KH or familial renal glucosuria KH, and NEK11-KH." (PMID 32034166, 2020).
pancreatic adenocarcinoma (1 paper, 2021). "To assess whether members of the NEK family (from NEK1 to NEK11) are associated with pancreatic cancer prognosis, we first compared their expression levels in tumors and normal tissue using pancreatic adenocarcinoma (PAAD) datasets from The Cancer Genome Atlas (TCGA) database." (PMID 34315872, 2021).
cancer (5 papers, 2013 to 2025). A tumor composed of atypical neoplastic, often pleomorphic cells that invade other tissues. "Nek11 research has been starting to focus on the relationship between Nek11 proteins and various cancers." (PMID 35409400, 2022). "Together, this provides a strong rationale for considering Nek11 as an attractive target for the development of novel DDR-based cancer therapeutics." (PMID 26501353, 2015). "Furthermore, targeting NEK11 could help overcome drug resistance in cancers where resistance to genotoxic chemotherapeutic agents is a challenge by preventing the repair of DNA damage induced by treatments." (PMID 41154634, 2025). "Indeed, modulating NEK11 activity could enhance the efficacy of cancer treatments, such as chemotherapy and radiation therapy, by hindering DDR pathways and promoting cancer cell apoptosis." (PMID 41154634, 2025). "In cancers, NEKs such as NEK1, NEK2, NEK6, and NEK11 promote genome instability and tumor progression, while others, like NEK1, paradoxically offer opportunities for radiosensitization." (PMID 41154634, 2025).
tumor (5 papers, 2015 to 2025). "One explanation for this could be that Nek11 is upregulated as a protective measure in early stage dysplastic cells, but is then lost in invasive tumours." (PMID 26501353, 2015).
NEK11 also shares sentences with these, for which no sentence is quoted: gastric cancer (2 papers); esophageal adenocarcinoma (1); familial melanoma (1); hepatopathy (1); Hypoglycemia (1); iron deficiency (1); melanoma (1); migraine (1); Obesity (1); pancreatic cancer (1); prostate carcinoma (1).